CDK4 (cyclin dependent kinase 4)
Diseases named in the same sentence as CDK4 in open-access papers (continued):
Sharing a sentence is not in itself a finding about the gene and the disease.
cancer (continued). "In this setting, metformin blocks both the mTOR signaling pathway and the senescence-associated reprogramming of cancer stemness induced by CDK4/6 inhibitor, a known Jekyll and Hyde of CDK4/6 inhibition in cancer treatment." (PMID 33494247, 2021). "We also found significant enrichment for known cancer driver genes from the COSMIC (Catalogue Of Somatic Mutations In Cancer) database in our predicted causal genes list, such as CDK4, EGFR, PTK6, and CCND1 (29/264; Fisher adjusted p < 0.01)." (PMID 34010657, 2021). "CDK4, a key factor associated with cell cycle regulation, is currently being utilised as an important target for cancer treatment." (PMID 34930213, 2021). "There are mutations or over-activation of CDK4/6 in a variety of cancer tissues, so CDK4/6 has always been regarded as an important target for drug development." (PMID 34249939, 2021). "p16INK4a (CDKN2A) is a critical component of the CDK4/6 complex, and its high protein expression in cancer cells often indicates Rb loss of function." (PMID 32626773, 2020). "The senescence-associated secretory phenotype (SASP) induced by CDK4/6 inhibitors has dual effects on cancer treatment." (PMID 33116117, 2020). "Although no detected mutations are directly associated with resistance against CDK4/6 inhibition, we found several mutations in cancer-associated genes possibly contributing to the acquired resistance against CDK4/6 inhibition." (PMID 32565737, 2020). "Our results suggested ATO induced cyclin D1 degradation has a similar effect to CDK4/6 inhibitors, caused inhibition of CDK4/6 signaling, induced cancer cell senescence, and inhibited SCC outgrowth in 4NQO induced OSCC and ESCC mouse models in vivo." (PMID 33046973, 2020). "IAP-based PROTACs caused a combined degradation of CDK4/6 and IAPs resulting in synergistic effects on cancer cell growth." (PMID 33133483, 2020). "CDK4 complexed with cyclin D isoforms, constitutes an established pharmacological target in several human cancers, associated with mutation of CDK4, amplification of cyclin D or overexpression of p16INK4a, all of which lead to hyperactivation of this kinase." (PMID 32104498, 2020). "Most significantly CDKN2A loss and RB1 loss are mutually exclusive in most cancers that lose these genes at a significant level (>5%), suggesting that the control of CDK4/6 activity and RB-status appear to define a single element of the pathway." (PMID 32242058, 2020). "The MAPK cascade and the CDK4/6 signaling complex are frequently deregulated or mutated in a variety of cancer types, which prompted the development of small molecular weight inhibitors that made it to clinic." (PMID 33255177, 2020). "Accordingly, inhibition of cyclin D-CDK4/6 kinase in RB-proficient cancer cells causes cell cycle arrest and/or senescence, whereas, RB-deficient cancer cells do not halt their proliferation upon CDK4/6 inhibition." (PMID 32249776, 2020). "Single copy loss on chromosome 13q encompassing the RB1 locus is prevalent in many cancers, yielding reduced expression of multiple genes in cis, and is inversely related to the CDK4/6-RB integrated signature supporting a cause-effect relationship." (PMID 32242058, 2020). "In this study, we analyzed the correlation between individual gene expression and mutation in TCGA pan-cancer cohort, and identified the CDK4/6 complex as the top candidate DRPCC." (PMID 32249776, 2020). "CDK4/6 activity is clinically relevant as mutations, deletions, and amplifications that increase CDK4/6 activity contribute to the progression of many cancers." (PMID 32255427, 2020). "It was also recently demonstrated that the activation of CDK4 (cyclin dependent kinase 4), which is frequently observed in cancer cells and linked to the inhibition of senescence, directly phosphorylates DNMT1 and blocks its degradation by autophagy." (PMID 31861179, 2019).
cancer (continued). "In most human cancer cells, this pathway is impaired due to either the loss of Rb itself, overexpression of cyclin D1, mutation of CDK4 (causing insensitivity to CDK inhibitors) or the loss of p16Ink4a." (PMID 30959874, 2019). "Nuclear PIKE-A associates with CDK4 and then disrupts CDK4-cyclinD1 complex and inhibits the Rb pathway, resulting in cancer cell cycle arrest." (PMID 30833542, 2019). "CDK4 is a key regulator in cell cycle progression, and the underlying p16 pathway is therefore frequently altered in various types of cancer." (PMID 30804704, 2019). "MDM2 downregulation is necessary for CDK4/6 inhibitor therapy-induced senescence in a variety of cancer cell lines, and the loss of MDM2 is observed post palbociclib treatment in patients with WD/DDLS who have prolonged periods of PFS." (PMID 29789718, 2018). "Our results further suggest that a subset of p16INK4a mutations will be most detrimental in cancer settings driven by CDK4." (PMID 29091774, 2017). "KTC1 cells show also deletion of P16 loss which is frequent in many cancers and results in the over-activation of CDK4/6 axis, critical to cell cycle entry." (PMID 29156680, 2017). "While cyclin D1:CDK4/6 complexes have a central role in regulating the initiation of the cell cycle, activating mutations in CDK4/6 are exceedingly rare in cancer." (PMID 26857361, 2016). "p16INK4a is the most frequently deleted locus in human cancer; its loss of function can result in a constitutively active CDK4/6, thus driving uncontrolled proliferation." (PMID 25914884, 2015). "Aberrant activity of CDK4/cyclin D1 has been implicated in several cancers, and blocking CDK4/cyclin D1 activity with Ox-1 was previously shown to be an effective anticancer therapy for pRb+ solid tumors." (PMID 26188358, 2015). "Deregulation of the cyclin D1/CDK4/6/Rb pathway leads to increased cell proliferation; this signaling axis is one of the most frequently mutated pathways in cancers." (PMID 26337082, 2015). "Among the CDKs, CDK4 is one of the genes most frequently affected by somatic genetic variations that are associated with various forms of cancer." (PMID 26252490, 2015). "Specifically, BMP-2 was shown to not only cause G1 arrest of monocultured cancer cells but also reduce the number of cells in S phase and their CDK4 expression." (PMID 25271422, 2014). "We have previously found in kinetic analyses from highly synchronized normal cells and p16-deficient cancer cells that cyclin D:Cdk4/6 is constitutively active throughout early G1 phase at the same time when Rb is repressing E2F target genes." (PMID 24876129, 2014). "A number of genetic aberrations that promote cancer lead to deregulated E2F activity, including mutations in pRb, cyclinD1, p16INK4a and CDK4." (PMID 17878947, 2007). "CDK4, a key regulator of the cell cycle, promotes cell proliferation, a hallmark of cancer." (PMID 41411347, 2025). "Thus, it is essential to comprehend the mechanisms underlying regulation of CDK4 overexpression in human cancer." (PMID 40299549, 2025). "In preclinical investigations, CDK4/6 inhibitors have enhanced apoptosis, caused cellular senescence, reduced DNA damage repair, and arrested the cell cycle, all of which have radiosensitized cancer cells." (PMID 40035822, 2025). "SKP2 inhibitors may be useful to treat RB-deficient cancers for which CDK4 inhibitors are ineffective and also show efficacy in resensitizing drug-resistant cancers and synergistic effects with other drugs." (PMID 40002221, 2025).
cancer (continued). "Notably, PROTACs degrading CDK4/6 have shown greater efficacy than traditional CDK4/6 kinase inhibitors in RB1-deficient cancer models, yet the mechanism behind this increased effectiveness remains to be clarified." (PMID 40940326, 2025). "It was reported that CDK4/6 inhibitors cause apoptosis in cancer cells." (PMID 38170401, 2024). "CDK4 deregulation is a well-established hallmark of various cancers." (PMID 38732173, 2024). "Besides testing the kinase mutations CDK6-R31C and CDK4-R24C we generated the murine homolog of p16INK4a displaying the cancer mutation P40L." (PMID 39088265, 2024). "As such, repurposing of CDK4/CDK6 inhibitors (such as Palboclicib) to treat KSHV-associated cancers may target multiple signaling pathways which will minimize drug resistances." (PMID 38365882, 2024). "Cancer cells might exhibit heightened expression of cyclin D1 or CDK4/6, causing overstimulation of the G1/S checkpoint and resistance to CDK4/6 inhibitors." (PMID 39001539, 2024). "Exploring the underlying mechanism of the CDK4/6 pathway in cancer cells and the drug interactions of CDK4/6 inhibitors in combination therapy could help identify new therapeutic strategies for ccRCC." (PMID 38890443, 2024). "In cancer, driver mutations elevate c-Myc levels, facilitating adaptation to CDK4/6 inhibitors." (PMID 38030655, 2023). "Flow cytometry analysis was also conducted to examine whether Cdk4 deficient cancer cells could induce immune cell infiltration and activation in TME." (PMID 37833461, 2023). "The oncogenic mutation in a normal cell which initiates cancer upregulates Cdk4." (PMID 37279947, 2023). "Therefore, the mechanisms underlying resistance to CDK4/6i and the development of new therapeutic strategies to circumvent such resistance is a hot topic in cancer research." (PMID 37835528, 2023). "Moreover, CDK4 deficiency has been found to affect cell proliferation in human malignant tumor cells." (PMID 37762324, 2023). "Control and Cdk4-deficient cancer cells were subcutaneously injected to immunocompetent mice." (PMID 37833461, 2023). "Our study aims to investigate whether a treatment method other than loperamide, a probiotic agent, S. boulardii, can also be effective in diarrhea associated with malignancy treatment, CDK4 and CDK6 inhibitors are used in this study." (PMID 36945921, 2023). "CDK4 was identified as a major risk factor for disease progression in Paget’s disease and its overexpression and/or hyperactivation is implicated in many types of human cancers." (PMID 36839989, 2023). "However, these treatments are ineffective for the large proportion of cancers that have CDK4/6 or Rb1 mutations." (PMID 37484531, 2023). "In cancer cells, cytoplasmic p27 may associate with CDK4/cyclin D1 complexes and promote CDK4 activity." (PMID 35216401, 2022). "Thus, the cyclin D-cdk4/6-Rb-E2F axis is a major regulator of the cell cycle and most human cancers display defects in this signaling pathway, e.g., loss of Rb or amplification of cyclin D and/or cdk4/6." (PMID 36091143, 2022). "Drug-resistant mutated forms of CDK4/6 implicated in cancers could also be destroyed using this technique." (PMID 35327487, 2022). "Moreover, in this type of cancer, up-regulation of a functional counterpart of CDK4/6, i.e. COL6A3 has been associated with shorter OS and advanced clinical stage." (PMID 36266723, 2022). "Interestingly, cell cycle arrest and western blotting studies showed the regulation of the cyclin-dependent kinase inhibitor (p21) and cyclin-dependent kinase 4 (Cdk-4)/Cyclin-D1 expression, causing cancer cell apoptosis." (PMID 36046355, 2022). "Laboratory data suggest that cancer cells with loss-of-function alterations of CDKN2A may be sensitive to CDK4/6 inhibitors such as Palbociclib, Ribociclib, and Abemaciclib." (PMID 36140642, 2022).
cancer (continued). "CDK4/6 play pivotal roles in the transition from the G1 to S phases by regulating the phosphorylation state of retinoblastoma-associated protein (Rb) and thus are essential for cell-cycle progression in many cancer cells." (PMID 35270034, 2022). "However, the long-term use of CDK4/6 inhibitors results in drug resistance and poor therapeutic effect on Rb-deficient tumors, especially some malignant tumors, which limits the clinical application of CDK4/6 inhibitors." (PMID 35592410, 2022). "In many cancers, this is due to loss of function of RB itself, however, in melanoma RB is often functional, and instead aberrant activation of this pathway is predominately driven by a loss of p16INK4a and, subsequently, constitutive CDK4/6 activity." (PMID 34025662, 2021). "Abnormal dysregulation of the CDK4/6-cyclin D1 complex is a hallmark of cancer." (PMID 34395284, 2021). "CDK4 in lysosome activates mTORC1 and is also associated with cancer progression." (PMID 33364954, 2020). "Moreover, activation of CDK–Rb–E2F signaling has often been associated with endocrine resistance; for this reason, CDK4/6 inhibitors, such as palbociclib, are investigated in clinical trials in ER+ cancer." (PMID 32351542, 2020). "Unexpectedly, inhibition of CDK4/6 also triggers the apoptosis of RB-deficient cancer cells." (PMID 32249776, 2020). "A variety of evidence indicates that the CDK4/6-Cyclin D/Rb/E2F pathway plays a relevant role in the regulation of cell energy metabolism, contributing to the metabolic reprogramming associated with cancer." (PMID 32708306, 2020). "Therefore, it remains necessary to further characterize the means by which other mechanisms cooperate or contribute to the CDK4/6i and PARPi synergistic effect in RB-deficient cancer cells." (PMID 32249776, 2020). "Cyclin Dependent Kinase 4 (CDK4), a member of the Ser/Thr protein kinase family, is a key player in cell cycle progression (G1 to S phase) and is implicated in the tumorigenesis of a variety of cancers." (PMID 32194984, 2020). "Cyclin-dependent kinase 4, encoded by CDK4, might play key roles in the tumorigenesis of a variety of cancers through deregulation of the CDK4/6–cyclin D–INK4–RB pathway." (PMID 30925583, 2019). "It has provided evidence that LKB1 deficient cancer cells were sensitive to CDK4/6 inhibitor based on the protein-protein interaction of LKB1/CDK4, supporting the kinase inhibitors function not only as kinase suppressor, but also as signaling regulator based on protein–protein interaction network." (PMID 31787897, 2019). "For example, CDK4 (Cyclin Dependent Kinase 4) has been implicated in a number of cancer types." (PMID 30704465, 2019). "Preclinical data indicates that cancers with a loss in p16INK4A may still be sensitive to CDK4 inhibition." (PMID 29670090, 2018). "RB1 deficiency makes cancer cells resistant to CDK4/6 inhibitors, but may also prevent efficient PARP1 gene targeting." (PMID 29306194, 2018). "Aberrant activation of CDK4 was closely associated with various kinds of carcinomas." (PMID 28095789, 2017). "In addition, mutation or amplification of CDK4 is associated with the transition from G1 to S phase and ultimately induces cancer cell growth." (PMID 27670681, 2016). "In general, cancers with p16 loss may also be sensitive to CDK4/CDK6 inhibition, with preclinical data supporting this in melanoma and lung cancer among others." (PMID 25914884, 2015). "Analyses of potential correlations between genetic alterations of Stat6, CDK4 and p27 expression could be decisive in clarifying the role of Stat6 in familial predisposition to certain cancers and/or failure of hormonal therapy." (PMID 24401087, 2014). "Furthermore, analysis of mutual-exclusivity in cancer demonstrates that there is a pronounced reciprocal relationship between the loss of p16ink4a, deregulation of CDK4/6, and loss of RB." (PMID 25156567, 2014). "Cdk4 pathway alterations have been linked to a number of cancers including CRC." (PMID 23530816, 2013).
cancer (continued). "One of the recent discovered Hsp 90 inhibitors is deguelin, here we found that deguelin depleted Hsp 90 client proteins including Akt, survivin and Cdk4 by disrupting the their association with Hsp 90, all these proteins are proven to be important for cancer development for HNSCC." (PMID 23372762, 2013). "However, the CDK4 IVS4-nt40 AA genotype is significantly associated with cancer and tumors/cancer in obese patients." (PMID 19327170, 2009). "Furthermore, mutations targeting SCFFbx4-αB crystallin in human cancers implicate ligase function in cyclin D1 overexpression and subsequent nuclear accumulation of active cyclin D1/CDK4 complexes." (PMID 18764945, 2008). "Two high-risk susceptibility genes have been identified (CDKN2A and CDK4) and gene–environment interactions may occur at several steps in cancer development." (PMID 15054457, 2004). "However, multiple immunohistochemical studies have demonstrated clear differentiation between the lesion and the primary pathology, particularly through the detection of MDM2 and CDK4 rearrangements, as well as evidence of deubiquitination in cancer-associated pathways." (PMID 40926903, 2025). "For malignant tumors, it is typical that cell cycle or proliferation is accelerated by oncogene mutation, and in LPS, this is associated with the high level of amplification of the chromosome 12q1315 region, including CDK4 and MDM2 (regarded as cell cycle oncogenes)." (PMID 39063036, 2024). "Therefore, exploring the underlying mechanism of the CDK4/6 pathway in cancer cells and the interactions of CDK4/6 inhibitors in combination therapy could help identify new therapeutic strategies for ccRCC." (PMID 38890443, 2024). "Indeed, RB1 inactivation has been linked to cancer initiation and progression and resistance to several targeted therapies, including androgen receptor (AR) antagonists, ER antagonists, CDK4/6 inhibitors, and EGFR tyrosine kinase inhibitors." (PMID 36928314, 2023). "Thus, targeting cancer-specific mutations in mitogenic signaling in combination with CDK4/6i may be an optimal strategy to minimize toxicity while maximizing their therapeutic outcomes." (PMID 38030655, 2023). "The R24C mutation prevents INK4-family CDK4 inhibition; in cancers, Cdk4-R24C mutation is synergistic with loss of function of Cip/Kip inhibitors, suggesting that Cdk4-R24C may counteract a damaging combination of loss of cyclin D2 with gain of p27 in IRS2 null β cells." (PMID 37712417, 2023). "In addition, CDK4 inhibition can also cause cancer cell apoptosis." (PMID 36106139, 2022). "Consequently signatures aimed at identifying tumors with CYCLIN D activation, RB loss of function or CDK4 inactivation are being explored in clinical samples to distinguish those cancers that are sensitive or resistant to CDK4/6 inhibitor therapies [reviewed in 161]." (PMID 36051751, 2022). "For example, pharmacologic inhibitors (such as palbociclib and abemaciclib) of CDKs 4 and 6 (CDK4/6) have shown significant inhibitory activities against several solid tumors, inducing G1 cell cycle arrest, causing quiescence, apoptosis, or senescence in various cancer cells." (PMID 34687270, 2022). "Oral/dental follow-up with personalized schedule should be planned for patients assuming CDK4/6 inhibitors and antiresorptive medications since these cancer treatments may represent an additional risk factor for the occurrence of medication osteonecrosis of the jaws." (PMID 33353034, 2020). "A variety of evidence suggest that the metabolic outcomes associated with CDK4/6 inhibition are context specific and CDK4/6 inhibitors may have different and even opposing effects on energy metabolism in different cancers or in the same cancer type depending on the conditions." (PMID 33072590, 2020).